RIDA (reactive intermediate imine deaminase A)
Description:
Catalyzes the hydrolytic deamination of enamine/imine intermediates that form during the course of normal metabolism. May facilitate the release of ammonia from these potentially toxic reactive metabolites, reducing their impact on cellular components. It may act on enamine/imine intermediates formed by several types of pyridoxal-5'-phosphate-dependent dehydratases including L-threonine dehydratase. Also promotes endoribonucleolytic cleavage of some transcripts by promoting recruitment of the ribonuclease P/MRP complex. Acts by bridging YTHDF2 and the ribonuclease P/MRP complex. RIDA/HRSP12 binds to N6-methyladenosine (m6A)-containing mRNAs containing a 5'-GGUUC-3' motif: cooperative binding of RIDA/HRSP12 and YTHDF2 to such transcripts lead to recruitment of the ribonuclease P/MRP complex and subsequent endoribonucleolytic cleavage.
Synonyms: hp14.5; p14.5; HRSP12; UK114; PSP
Tractability: Small molecule: it has a binding pocket of medium quality. PROTAC: ubiquitination databases record sites on it.
Gene: Protein-coding gene on chromosome 8 (98,102,336 to 98,117,175, reverse strand). Ensembl gene ENSG00000132541.
Subcellular location: Cytoplasm; Nucleus; Peroxisome; Mitochondrion
Pathways (Reactome):
Metabolism: Threonine catabolism
Gene Ontology:
Molecular function: 2-iminobutanoate deaminase activity; 2-iminopropanoate deaminase activity; mRNA binding; protein binding; RNA binding; RNA endonuclease activity producing 3'-phosphomonoesters, hydrolytic mechanism; 2-iminobutanoate/2-iminopropanoate deaminase; hydrolase activity
Biological process: mRNA catabolic process; mRNA destabilization; L-threonine catabolic process; negative regulation of translation; negative regulation of gene expression; post-transcriptional regulation of gene expression
Cellular component: cytoplasm; extracellular exosome; mitochondrion; nucleus; cytosol; mitochondrial matrix; peroxisome
Genetic constraint (gnomAD): Loss-of-function variants: 5 observed, 7.2 expected, observed/expected ratio (o/e) 0.69, 90% interval 0.36 to 1.44. That is too few expected variants to judge how well the gene tolerates losing a copy. Missense variants: 71 observed, 81.29 expected, observed/expected ratio (o/e) 0.87, 90% interval 0.72 to 1.06. Synonymous variants: 21 observed, 27.57 expected, observed/expected ratio (o/e) 0.76, 90% interval 0.54 to 1.1.
Homologues: Orthologues: chimpanzee RIDA (99% identical), dog RIDA (92% identical), pig RIDA (88% identical), rat Rida (88% identical), guinea pig RIDA (82% identical), mouse Rida (80% identical), tropical clawed frog rida (77% identical), zebrafish rida (72% identical), macaque RIDA (68% identical), Caenorhabditis elegans C23G10.2 (62% identical), Drosophila melanogaster UK114 (47% identical).
Diseases named in the same sentence as RIDA in open-access papers:
RIDA is named in the same sentence as 10 diseases in open-access papers, as found by Europe PMC text mining. Sharing a sentence is not in itself a finding about the gene and the disease. The quoted sentences say what the papers report.
Wilms tumor (1 paper, 2024). An embryonal neoplasm characterized by the presence of epithelial, mesenchymal, and blastema components. "The identified prognostic genes, particularly GRAMD1A, SPR, EBAG9, RBM47, and RIDA, offer significant potential as both prognostic biomarkers and therapeutic targets for improving personalized treatment in Wilms tumor patients." (PMID 39659787, 2024).
RIDA also shares sentences with these, for which no sentence is quoted: diabetic retinopathy (2 papers); proliferative diabetic retinopathy (2); tumor (2); adeno-carcinoma (1); Burkitt lymphoma (1); cognitive decline (1); hepatocellular carcinoma (1); infection (1); kidney diseases (1).